DYNC2I1 (dynein 2 intermediate chain 1)
Description:
Acts as one of several non-catalytic accessory components of the cytoplasmic dynein 2 complex (dynein-2 complex), a motor protein complex that drives the movement of cargos along microtubules within cilia and flagella in concert with the intraflagellar transport (IFT) system. DYNC2I1 plays a major role in retrograde ciliary protein trafficking in cilia and flagella. Also requires to maintain a functional transition zone.
Synonyms: WDR60; FLJ10300; FAP163; CFAP163; DIC6; SRPS6; SRTD8
Tractability: Small molecule: a structure with a bound ligand is known. PROTAC: ubiquitination databases record sites on it.
Gene: Protein-coding gene on chromosome 7 (158,856,558 to 158,956,747, forward strand). Ensembl gene ENSG00000126870.
Subcellular location: Cell projection, cilium; Cytoplasm, cytoskeleton, microtubule organizing center, centrosome
Subcellular location (Human Protein Atlas): Basal body; Centrosome; Cytosol; Primary cilium
Pathways (Reactome):
Organelle biogenesis and maintenance: Intraflagellar transport
Gene Ontology:
Molecular function: dynein light chain binding; protein binding; dynein heavy chain binding
Biological process: cilium assembly; embryonic skeletal system morphogenesis; intraciliary retrograde transport; intraciliary transport
Cellular component: centrosome; ciliary base; cilium; cytoplasmic dynein complex; extracellular region; interphase microtubule organizing center; pericentriolar material; spindle pole; ciliary tip; dynein complex; male germ cell nucleus
Genetic constraint (gnomAD): Loss-of-function variants: 79 observed, 118.82 expected, observed/expected ratio (o/e) 0.66, 90% interval 0.55 to 0.8. The upper end of that interval is the gene's LOEUF score, 0.8, which puts it in group 3 of 6, group 1 being the genes least tolerant of losing a copy. Missense variants: 1,214 observed, 1,268.4 expected, observed/expected ratio (o/e) 0.96, 90% interval 0.91 to 1. Synonymous variants: 476 observed, 474.74 expected, observed/expected ratio (o/e) 1, 90% interval 0.93 to 1.08.
Gene-disease validity (ClinGen):
ClinGen rates the evidence that DYNC2I1 causes each of these diseases.
short-rib thoracic dysplasia 8 with or without polydactyly (autosomal recessive): Definitive.
Homologues: Orthologues: macaque DYNC2I1 (95% identical), chimpanzee DYNC2I1 (86% identical), rabbit DYNC2I1 (79% identical), rat Dync2i1 (71% identical), mouse Dync2i1 (70% identical), pig DYNC2I1 (70% identical), guinea pig DYNC2I1 (69% identical), dog DYNC2I1 (67% identical), tropical clawed frog dync2i1 (42% identical), zebrafish dync2i1 (38% identical), Caenorhabditis elegans wdr-60 (15% identical). Paralogues in human: DYNC2I2 (11% identical), DNAI4 (11% identical), DNAI3 (10% identical), DYNC1I2 (10% identical), DNAI1 (10% identical), DYNC1I1 (10% identical), DNAI2 (8% identical).
Diseases named in the same sentence as DYNC2I1 in open-access papers:
DYNC2I1 is named in the same sentence as 15 diseases in open-access papers, as found by Europe PMC text mining. Sharing a sentence is not in itself a finding about the gene and the disease.
DYNC2I1 shares sentences with these, for which no sentence is quoted: ciliopathies (4 papers); Jeune syndrome (4); Tumor (2); Behcet’s syndrome (1); cancer (1); depression (1); epilepsy (1); genetic disease (1); infection (1); Intellectual disability (1); polydactyly (1); retinal degeneration (1); schizophrenia (1); short rib-polydactyly syndrome (1); Tourette syndrome (1).